IL1B (interleukin 1 beta)
Diseases named in the same sentence as IL1B in open-access papers (continued):
Sharing a sentence is not in itself a finding about the gene and the disease.
periodontitis (continued). "Thus, as evident herein with the elevated levels of miR-155 in the whole blood of P, AS-C and AS-P patient groups, compared to the C group; elevated miR-155 levels in periodontitis and CHD patients are often accompanied by higher salivary IL-1β levels and changes in clinical periodontal parameters." (PMID 37974134, 2023). "However, the difference in IL-1β concentration among healthy individuals and initial periodontitis cases was not significant." (PMID 35270581, 2022). "Studies have been shown that PLEK is significantly over-expressed in periodontitis, cardiovascular disease, rheumatoid arthritis, and ulcerative colitis, and thought to be a crucial mediator in the secretion and activation pathways of pro-inflammatory cytokines TNF-α and IL-1β." (PMID 36258174, 2022). "In addition, the frequency detection of F. nucleatum was found to be significantly higher in periodontitis sites in IL-1B(3954)-SNP positive compared to IL-1B(3954)-SNP negative subjects." (PMID 35122548, 2022). "The present study aimed to evaluate 3 biomarkers (i.e., IL-1β, IL-6, and MMP-8) out of the 5 most promising salivary host-derived biomarkers identified by recent systematic reviews and meta-analyses as good candidates to be chosen for the early diagnosis of periodontitis." (PMID 35368315, 2022). "B. lactis HN019 application could markedly decrease the levels of IL-1β and the ratio of RANKL/OPG in rats with periodontitis and metabolic syndrome and could downregulate the expression of TNF-α and IL-6 in rats only with periodontitis." (PMID 35402306, 2022). "Unlike those from healthy individuals, OBMC-derived supernatants from periodontitis patients exhibited decreased ability to induce secretion of IFN-γ by allogeneic healthy PBMCs treated with IL-2, while they triggered significant levels of TNF-α, IL-1β and IL-6 by untreated PBMCs." (PMID 33672708, 2021). "High glucose (HG) was shown to induce Toll like receptor 2 (TLR-2), NF-ĸB pathway and IL-1β in human gingival fibroblasts and RAGEs were upregulated on mRNA level in inflamed gingival tissues of T2DM periodontitis patients compared to their non diabetic periodontitis patients." (PMID 34940355, 2021). "Pro-inflammatory cytokines, such as IL-1β, IL-6, and TNF-α, are representative co-related molecules involved in the induction and regulation of the inflammatory cascade in systemic inflammatory disorders, including RA, periodontitis, and gut inflammatory diseases." (PMID 33716675, 2021). "After logistic regression analysis, the combination of IL-1β, ICTP, and Pg not only yielded the best AUC value to discriminate periodontitis patients from healthy subjects, but also exhibited the best ability to discriminate periodontitis subjects from gingivitis subjects (AUC = 0.77)." (PMID 34001101, 2021). "However, IL-1β did not significantly decrease in the periodontitis-stress group following ligature removal." (PMID 34950607, 2021). "We demonstrated that IL-1β and ICTP in combination yielded a similar AUC value (0.917) to differentiate periodontitis subjects from healthy subjects when compared to the combination of IL-1β, MMP-8, and Pg (0.920), indicating that IL-1β and ICTP are more effective for predicting periodontitis." (PMID 34001101, 2021). "In the other part, periodontitis, through bacteria or their virulence factor translocation, act like a constant challenge to immune inflammatory cells, increasing the release of pro-inflammatory mediators (CRP, TNF-α, IL-6, and IL-1β) and periodontal-derived EVs into circulation." (PMID 34769262, 2021). "Furthermore, animal studies have provided some evidence to show that miR-146a exerts anti-inflammatory impacts in periodontitis through inhibiting the expressions of the pro-inflammatory cytokines such as tumor necrosis factor-alpha (TNF-α), interleukin-1β (IL-1β), and IL-6 in periodontal tissue." (PMID 34645448, 2021).
periodontitis (continued). "Besides, the existence of elevated cytokines expression comprising pro‐inflammatory and regulatory cytokines such as IL‐1β, interferon (IFN)‐γ, IL‐1 receptor antagonist (RA), IL‐4, IL‐6, IL‐10, IL‐12, TNF‐α, and induced protein (IP)‐10, lead the way to periodontitis’ inflammatory process." (PMID 34272761, 2021). "Previously, our group reported that IL-1β and butyric acid, which are both up-regulators of CYP27B1, could be detected in the gingival crevicular fluids of patients with periodontitis, and the concentrations were positively correlated with periodontal inflammation." (PMID 33505780, 2021). "In addition, one of the most important key factors responsible for periodontal destruction is the upregulation of inflammatory cytokines, including IL-1β, IL-6, and TNF-α, in the inflammatory sites of periodontal tissue; these cytokines are mainly involved in the pathogenesis of periodontitis." (PMID 33287198, 2020). "In addition, PGFE effectively regulated the expression of the pro-inflammatory cytokines IL-6, IL-1β, and TNF-α, which play an important role in the regulation of periodontitis in PG-LPS-stimulated HPDL cells, and it effectively suppressed the mRNA levels of these pro-inflammatory cytokines." (PMID 33287198, 2020). "Of particular interest, in periodontitis patients, IL-36γ mRNA is positively correlated with archetypal inflammatory cytokines already known to be involved in periodontitis and inflammatory diseases, i.e., IL-1β, IL-6, TNF-α and IL-17A while IL-36β or IL-36Ra are not correlated with these cytokines." (PMID 31848404, 2019). "A reduced expression of inflammatory molecules, such as IL-1β, TNF-α and IL-17, following quercetin treatment (3.3 × 10−4 mol/kg), has been shown to also negatively affect RANKL expression and downregulation of the adhesion molecule ICAM-1 in a mouse periodontitis model." (PMID 29200988, 2017). "In addition the amount of IL-1β in nonsmoker healthy group was statistically lower than nonsmoker periodontitis patients (p=0.011)." (PMID 29299075, 2017). "Accordingly, ILC3s of periodontal tissues from control animals (i.e., without periodontitis) display more marked CCR6 expression either without or with IL-1β/IL-23 treatment compared to those of periodontitis model; however, the effect was more marked for cytokines-treated ILC3s." (PMID 28861078, 2017). "In this specific experimental periodontitis mouse model, the investigators have noted increased expression of RANKL and an increase in osteoclast activity; moreover, in line with the function of Socs-3, they showed an increased expression of pro-inflammatory cytokines such as IL-1β and IL-6." (PMID 29163477, 2017). "In addition, the level of IL-1β gene expression in smokers was significantly less than nonsmokers in periodontitis group." (PMID 29299075, 2017). "Although IL‐1β is closely associated with inflammation and subsequent tissue destruction in rheumatoid arthritis and periodontitis primarily by the acceleration of fibrosis 32, 33, the involvement of IL‐1β in pathologic fibrosis in muscle tissue has not yet been studied." (PMID 27619557, 2017). "In conclusion, the results of the present investigation suggest that anethole may have a potent inhibitory effect on periodontitis through suppression of pro-inflammatory molecules (i.e. IL-1β and TNF-α); therefore it could be a novel therapeutic strategy for periodontitis." (PMID 25587321, 2014). "On the other hand, it has already been well documented that pathogenesis of chronic periodontitis may be determined by a pro-inflammatory response of cytokines, expressed in particular by secretion of tumor necrosis factor (TNF)-α, interleukin (IL)-1β and IL-17." (PMID 24509697, 2014).
periodontitis (continued). "We suggest that the strong HtrA1 positivity observed in plasma cells of tissues from patients affected by chronic and aggressive periodontitis could reduce the inhibitory effects of TGF-β, allowing the increase of inflammatory mediators (TNF-α; IL-1β) promoting disease progression." (PMID 24979214, 2014). "Thus, considering all the GCF samples (from periodontitis patients and controls), the percentage of samples considered below the detection level were 13% for IL-1β, 31% for IL-6, 3% for IL-10 and 5% for TNF-α (data not shown)." (PMID 24944641, 2014). "RANKL stimulates bone resorption and is upregulated by IL-1β and IL-6 among other cytokines; thus the ratio of RANKL and its natural antagonist osteoprotegerin (OPG) is a particularly important factor in determining bone cell resorption and turnover and this ratio is elevated in periodontitis." (PMID 24944840, 2014). "On the other hand the factors (selection criteria, ethnicity) along with the severity of the disease may partially explain why we were not able to find any association of periodontitis with other SNPs such as INF-γ, IL-1β, IL-6." (PMID 24274085, 2013). "Our data from studies of cultured fibroblasts showed that PTPα is indeed an important mediator of IL-1β signaling, which mediates activation of mitogen-activated protein kinases (e.g. ERK) and MMP-3 expression, which is important for connective tissue destruction in periodontitis." (PMID 23940616, 2013). "In addition, it has been documented that, both in patients with chronic periodontitis and T2DM, and in human gingival epithelial cells (HGEC) exposed to lipopolysaccharide (LPS) and high glucose concentrations, a significant increase in the expression of the NLRP3 inflammasome and IL-1β is observed." (PMID 41009326, 2025). "It has been found that CA treatment of LPS-induced Human gingival fibroblasts (HGFs) inhibited NLRP3 expression and reduced IL-1β and IL-18 levels while increasing NRF2 and HO-1 expression and reducing oxidative stress, suggesting that CA could attenuate inflammation in HGFs during periodontitis." (PMID 39456522, 2024). "Thus, the objective of this study was to evaluate the concentrations of salivary-17A, interleukin-1 beta, and interleukin-18 in patients with celiac disease who are on a gluten-free diet, both with and without periodontitis, and to compare these levels with those in healthy individuals." (PMID 38756445, 2024). "Therefore, a correlation may exist between periodontal tissues destruction, CHD and elevated IL-1β levels in saliva; and provide evidence for miR-155 having a role in modulating periodontitis in patients, with and without clinically diagnosed CHD." (PMID 37974134, 2023). "CD14+ monocytes secrete a variety of cytokines, including TNF-α, IL-1β, IL-6, IL-8, CCL2, CCL3, and CCL5, compared to CD14− cells from GCF in patients with periodontitis, which suggests that CD14+ monocytes may be a source of CCL5 in GCF and gingival tissue in patients with periodontitis." (PMID 38139161, 2023). "However, our study found high concentrations of IL-1β in saliva (p = 0.057) from G2 (P) and G4 (P-OSA) compared to G1 (H) and found that 80% of patients of both groups had the highest concentration of IL-1β (40–60 pg/mL), a determinant cytokine in periodontitis." (PMID 36967976, 2023). "Distinct and independent processes in NLRP3 inflammasomes in vitro are shown to elicit IL-1B and IL-18 production in response to non-canonical stimulation, which can fine-tune the pyroptosis response and is likely to account for the opposing patterns observed in periodontitis samples." (PMID 35844512, 2022). "Interestingly, elevated salivary levels of pro-inflammatory cytokines including Tumor Necrosis Factor (TNF)-α and Interleukin (IL)-1β and molecules involved in tissue degradation such as Matrix Metalloproteinase (MMP)-8 and -9 has been reported in saliva from patients with periodontitis." (PMID 26799067, 2016).
periodontitis (continued). "The results support the hypothesis that proinflammatory cytokines, including IL-1α, IL-1β and IL-6, are likely to be involved in the pathogenesis of periodontitis and are good markers to evaluate the success of nonsurgical therapy in disease sites of patients with periodontitis." (PMID 24944641, 2014). "In patients with poorly controlled type 2 diabetes, those with chronic periodontitis displayed higher caspase-1 mRNA levels and elevated protein levels of NLRP3, ASC, and IL-1β compared with periodontitis patients who were not diabetic." (PMID 41440367, 2025). "In severe periodontitis, TNF-α levels differed significantly between groups, while IL-1β did not, with mean cytokine levels lower in the impaired group." (PMID 41149360, 2025). "Although previous studies have examined the role of IL-18 and GSDMD in the destruction of periodontal tissue and in atherosclerosis, data is scarce regarding the salivary levels of IL-1β, IL-18, and GSDMD in patients with periodontitis, with and without CHD." (PMID 39071510, 2024). "As a result, the study’s aim was to investigate the levels of salivary IL-17A, IL-18, and IL-1B in celiac disease patients on GFD with and without periodontitis compared to healthy controls." (PMID 38756445, 2024). "The findings suggested that MBG did not have an impact on the expression of inflammatory genes (IL-1β, IL-6, iNOS and TNF-α) that were activated in the periodontitis microenvironment." (PMID 38449005, 2024). "MMP-8, MMP-9, IL-1β, IL-6, and Hb have been effective salivary biomarkers for detecting periodontitis in systemically healthy individuals, while MMP-9 and IL-1β also perform well in identifying non-periodontitis conditions." (PMID 39554809, 2024). "We found that the IL-1β levels were higher in the periodontitis III/IV patients in comparison with the periodontally healthy controls (p < 0.01) and with the periodontitis I/II patients (although not achieving statistical significancy)." (PMID 36769650, 2023). "TNF-α enhances the expression of IL-1β, IL-6, and RANKL; however, its level in the gingival crevicular fluid (GCF) does not considerably differ before and after periodontitis treatment." (PMID 38002398, 2023). "There was a significant positive correlation between stage IV periodontitis and salivary IL-33 (rs = 0.531) in G4 (P-OSA), and there was a significant negative correlation between stage II periodontitis and GCF IL-1β (rs = −0.510, p < 0.05) in G2 (P)." (PMID 36967976, 2023). "Lastly, the biomarkers such as TNF-α and IL-1β, which are targeted by FGF21 and involved in periodontitis development, were not determined in the present study." (PMID 36474191, 2022). "The pooled standardized mean difference of IL-1β and MMP-8 was −1.04 and 35.90, respectively, but the differences between periodontitis patients and healthy controls were not significant." (PMID 33383828, 2020). "In this study, levels of IL1β and IL12 in normal and gingival tissues with periodontitis in smokers and nonsmokers were determined through Real-time PCR method." (PMID 29299075, 2017). "The results of the present study showed that FUCO administration did not have a significant effect on serum TNF-α, IL-1β, or IL-6 levels or local OPG activity, which increased significantly in rats with periodontitis." (PMID 27043583, 2016). "Levels of IL-1β and IL-10 in GCF of patients with chronic periodontitis have been significantly altered in diseased versus nondiseased sites and tended to return to normal values after a 32-week periodontal therapy." (PMID 26977121, 2016). "Periodontitis induced by heat-killed Pg did not further increase the total bacterial load but led to increased gene expression levels of MCP-1, TNF-α, and IL-1β in the gums of AD mice and CRP levels in the plasma." (PMID 36915108, 2023).
periodontitis (continued). "The aim of the present exploratory subanalysis was to evaluate the role of the IL-1A −889, IL-1B +3954, IL-4 −34, IL-4 −590, GATA-3 IVS4 +1468 and COX-2 −1195 gene loci in patients with periodontitis after a non-surgical periodontal therapy with or without additional adjunctive systemic antibiotics." (PMID 35806269, 2022). "An overexpression of miRNA-146 in patients with rapidly progressive aggressive periodontitis was shown to be accompanied by a reduction in the levels of TNF-α, IL-1β, and IL-6, which suggests the existence of a negative feedback loop between mi-146 and pro-inflammatory cytokine synthesis." (PMID 35269617, 2022). "In this work, we also confirmed that the activation of caspase-4/11 was elevated in human periodontitis samples and in murine periodontitis models and that P. gingivalis (a gram-negative periodontopathogen) induced PDLSC pyroptosis with the cleavage of GSDMD and IL-1β release." (PMID 33869229, 2021). "However, plasma IL-1β, tumour necrosis factor-alpha (TNF-α), and metalloproteinase 8 (MMP-8) levels were not altered significantly by the induction of periodontitis or propolis treatment." (PMID 34070497, 2021). "Furthermore, various studies demonstrated increases in the expression of NLRP3, AIM2, IL-1β, and IL-18, but not ASC or NLRP2, in gingival tissue from periodontitis patients when compared to healthy individuals." (PMID 31341421, 2019). "Among patients with periodontitis, no predictive cutoff value could be established for any of the four pro-inflammatory markers regarding the presence or absence of periodontitis (NLRP3 in saliva and serum; IL-1β in saliva and serum)." (PMID 40572711, 2025). "Because periodontitis is also induced by gram-negative bacterial LPS, it may be potentially regulated through similar mechanisms; this is supported by the in vivo findings of this study, where BTH application resulted in decreased IL-1β levels." (PMID 40863312, 2025). "In addition, this study found that there was no significant improvement in IL-1β and TNF-α in periodontitis patients after NSPT, which may be related to the small sample size." (PMID 38877442, 2024). "However, after periodontal therapy, smoking periodontitis patients showed significantly higher IL-1β levels in their GCF than nonsmoking patients, which indicates that smoking may impair the response of periodontitis to periodontal treatment." (PMID 36726081, 2023). "Therefore, the primary aim of this preliminary study was to investigate GCF levels of IL-1β, IL-9, TNF-α, and VEGF before and after non-surgical periodontal treatment in patients suffering from stage III periodontitis with moderate and rapid rates of progression." (PMID 33218047, 2020). "In periodontal diseases, upregulation of IL-1β protein and NLRP3 inflammasome has also been demonstrated in periodontal tissues of uncontrolled type 2 diabetic patients with periodontitis, who exhibit more alveolar bone damage, compared with nondiabetic periodontitis patients." (PMID 31146750, 2019). "In wild‐type periodontitis mice, NAC‐S2 administration decreased the cemento‐enamel‐junction–alveolar bone crest (CEJ‐ABC) distance and the relative mRNA expression of TNF, IL‐6, and IL‐1β, while such phenomena could not be observed in TLR4 deficiency or Myd88 deficiency mice." (PMID 37647428, 2023).